C9orf153 (chromosome 9 open reading frame 153)
Synonyms: bA507D14.1
Tractability: Antibody: the Human Protein Atlas places it where antibodies can reach.
Gene: Protein-coding gene on chromosome 9 (86,220,265 to 86,259,657, reverse strand). Ensembl gene ENSG00000187753.
Subcellular location (Human Protein Atlas): Nuclear bodies; Plasma membrane; Nucleoplasm; Vesicles
Genetic constraint (gnomAD): Loss-of-function variants: 9 observed, 5.33 expected, observed/expected ratio (o/e) 1.69, 90% interval 0.93 to 1.95. That is too few expected variants to judge how well the gene tolerates losing a copy. Missense variants: 68 observed, 70.36 expected, observed/expected ratio (o/e) 0.97, 90% interval 0.79 to 1.18. Synonymous variants: 20 observed, 26.26 expected, observed/expected ratio (o/e) 0.76, 90% interval 0.54 to 1.11.
Homologues: Orthologues: dog C9orf153 (53% identical).